AURKA (aurora kinase A)
Diseases named in the same sentence as AURKA in open-access papers (continued):
Sharing a sentence is not in itself a finding about the gene and the disease.
cancer (continued). "Molecular and functional studies identified several oncogenic functions of constitutively overexpressed AURKA in cancer." (PMID 31740746, 2019). "AURKA leads to uncontrolled proliferation of cancer cells by phosphorylating RASSF1A and disrupting RASSF1A interactions with microtubules." (PMID 31706255, 2019). "Because AURKA is upregulated in cancers, efforts have been made to target the protein to aid in tumor reduction." (PMID 30679932, 2019). "Upon AURKA suppression, cancer cells become sensitive to chemotherapeutics and overall tumor growth is suppressed in a variety of cancer cells (docetaxel and taxane)." (PMID 30679932, 2019). "Our findings agree with earlier results showing a synergistic effect of alisertib (AURKA inhibitor) and cisplatin in cancer cells." (PMID 31740746, 2019). "Deregulation of Aurora kinase A (Aur-A), a member of the mitotic serine/threonine Aurora kinase family, and overactivation of the mTOR pathway commonly occur in multiple cancer types." (PMID 31406104, 2019). "Targeting AURKA expression or activity by inducing p27 degradation and Bax cleavage provided a promising new anti-cancer therapeutic." (PMID 30013101, 2018). "AURKA has been increasingly recognized as a target for cancer therapy due to its high expression in many cancer types." (PMID 30097580, 2018). "Here, we reveal that AURKA is located and imported in mitochondria in several human cancer cell lines." (PMID 30070631, 2018). "Our findings are further strengthened by recent two reports showing that two other components of the SWI/SNF complex are involved in the downregulation of AURKA expression and cancer cell sensitivity to AURKA inhibitors." (PMID 30097580, 2018). "Although still at a preclinical level, the only promising strategy appears to be the combination of AURKA inhibitors with agents simultaneously targeting multiple cancer-relevant AURKA partners and functions." (PMID 30070631, 2018). "Aurora A kinase (AURKA) is overexpressed in 96% of human cancers and is considered an independent marker of poor prognosis." (PMID 30544746, 2018). "Our work paves the way to anti-cancer therapeutics based on the simultaneous targeting of mitochondrial functions and AURKA inhibition." (PMID 30070631, 2018). "These roles of AURKA are conserved in four carcinoma cell lines, further increasing the relevance of these results." (PMID 30070631, 2018). "Overall, AURKA is the most prognostic gene in the TCGA cancer cohorts in which the median time of 2 years suggests that it is an indicator of early relapse as measured by OS." (PMID 32913979, 2017). "By comparing the clinical outcomes in the subsets, we observed that the cancers that expressed high levels of AURKA and low levels of NNMT had the worst outcomes and were associated with the shortest disease-specific survival." (PMID 28102366, 2017). "AURKA, a chromosome segregation related kinase, is yet another example of the danger of an overexpressed kinase in cancer." (PMID 29044188, 2017). "Last, many molecules associated with general cancer mechanisms were regulated including bcatenin, HIF1α, MYC or aurora kinase A." (PMID 29299138, 2017). "Overexpression or activation of Myc and AURKA are commonly simultaneously detected in human cancers." (PMID 28147341, 2017). "Nevertheless, to devise better chemotherapeutic strategies to target AURKA to eliminate cancer stem cells, a comprehensive understanding of the nuclear AURKA molecular network and nucleus translocation mechanism is required." (PMID 28114286, 2017). "Genetic amplification and mRNA and protein overexpression of AURKA are common in many different tumors, which have allowed aurora kinase A to be a potential target for development of cancer therapeutics in early-phase clinical trials." (PMID 28969025, 2017). "In the MD Anderson cohort 29% of luminal cancers showed overexpression of AURKA and downregulation of NNMT." (PMID 28102366, 2017).
cancer (continued). "Of note, there are accumulating lines of evidence that show that AURKA can regulate c‐MYC in cancer." (PMID 28417568, 2017). "Recently, it's demonstrated that AURKA is overexpressed, distributed beyond the nucleus in cancer cells and involved in the tumorigenesis through multiple mechanisms." (PMID 28147341, 2017). "The result showed that FOXM1 overexpression significantly increased the expression levels of AURKA as well as cancer stem cell markers c-Myc and Nanog, in MCF-7 cells." (PMID 28114286, 2017). "Positive AURKA protein expression was found in 12% (13/106) of hormone-naïve prostatectomy cancers, 47% (59/126) of local CRPC samples and 22% (23/104) of CRPC metastases." (PMID 29269934, 2017). "Most of the interacting genes, including FAM83D, TPX2, and AURKA, are all located on 20q, which is frequently amplified across many cancer types." (PMID 29088801, 2017). "ALDH1A1 also reciprocates and prevents AURKA degradation, thereby triggering a positive feedback activation loop which drives highly aggressive phenotypes in cancer." (PMID 28193222, 2017). "Inhibition of AURKA with MLN8237 (alisertib) alone or in combination with CDDP significantly suppressed viability of CDDP‐resistant cancer cells (P < 0.01)." (PMID 28417568, 2017). "We propose targeting AURKA as an effective second‐line therapeutic approach in cisplatin‐resistant cancers." (PMID 28417568, 2017). "In accordance with these findings, amplification, overexpression, and/or constitutive activation of AURKA have been reported in many types of human cancers and cancer cell lines." (PMID 28903390, 2017). "To validate the role of AURKA in cancer cell invasion, we built up a tet-on shRNA system to down-regulate AURKA expression in MDA-MB-231 cells (shAURKA MDA-MB-231)." (PMID 28592839, 2017). "It has been reported that disruption expression or kinase activity of AURKA or AURKB in cancer cells impairs mitotic progression and results in G2/M phase arrest." (PMID 28595628, 2017). "Most of these genes were expressed across all tumor cells, however, a few cancer genes, including AURKA and TOP2A, were restricted to a minor subpopulation." (PMID 28794488, 2017). "SMARCA4 is mutated or deleted in more cancer types than NSCLC36, 37, 43, and a relationship between SNF5 mutations and AURKA was reported for rhabdoid tumours." (PMID 28102363, 2017). "In agreement, inhibition of AURKA synergistically enhanced the cytotoxic effect of DNA-damaging agents in cancer cells by suppressing Survivin expression." (PMID 28218735, 2017). "The role and profile of AURKA has made it an attractive target for anti-cancer therapies, with a range of inhibitors under investigation." (PMID 27271876, 2016). "AURKA expression was detected by qRT‐PCR in all of the cancer samples, and there was also homogeneous expression in the noncancerous gastric mucosa of cancer patients." (PMID 26778597, 2016). "Alterations in aurora kinase A (AURKA) activity can result in mitotic errors and have been associated with cancer progression." (PMID 27624869, 2016). "This study provides novel insights into an undisclosed role for the kinase AurkA in self-renewal and migration of BCICs affecting response to cancer therapies, metastatic spread and recurrence." (PMID 27341528, 2016). "Fourteen genes that are essential to prevent EDR in cancer cells also are essential to prevent aneuploidy in mice [AURKA, BUB1B, BUB3, KIF11, MAD2L1, TPX2, TTK, SGOL1." (PMID 27144335, 2016). "Mechanistic studies in MV4-11 and HCT-116 cell lines suggest that the cancer relevant targets AURKA/FLT3 are inhibited inside the cells." (PMID 27863392, 2016). "Reversine has been shown to inhibit cancer cells through the cell cycle regulator proteins Aurora kinase-A (Aur-A) and -B (Aur-B), JAK2 and SRC." (PMID 27385117, 2016).
cancer (continued). "The AURKA gene on chromosome 20q13 is amplified, or Aurora A is overexpressed, in a wide range of cancers including bladder, breast, colorectal, gastric, head and neck, liver, lung, neuronal, ovarian, and prostate cancer, leukemia and lymphoma." (PMID 27713168, 2016). "Several studies have reported that Myc and AURKA directly regulate each other at the transcriptional level in various cancer cells." (PMID 27636990, 2016). "AURKA and AURKB are also overexpressed in a variety of human cancers, and the activation of AURKA and AURKB has oncogenic effects." (PMID 27636990, 2016). "There is emerging evidence to suggest that AURKA also promotes cancer development through mechanisms independently of its kinase activity." (PMID 26782714, 2016). "Consistent with this, a similar expression pattern of nuclear AURKA was observed with immunohistochemistry (IHC) staining and in the nuclear fraction of all cancer cells lines tested." (PMID 26782714, 2016). "Aurora A is widely overexpressed in many cancers, suggesting that inhibition of the Aurora kinase A is a potential target for cancer therapy." (PMID 27713168, 2016). "Collectively, these data suggest that inhibition of Aurora kinase A using TC-A2317 is a promising target for anti-cancer therapeutics." (PMID 27713168, 2016). "Tumorigenesis is strongly related to abnormal amplification and expression of AURKA, which has led to the recognition of AURKA as an important molecular target for cancer therapy." (PMID 26036635, 2015). "Given the specific localization and function in cells and pathological activation of AURKA in many malignant diseases, AURKA have been an attractive target for the development of new therapeutic approaches for cancer treatment." (PMID 26729093, 2015). "The silencing of AURKA by shRNAs or small molecular inhibitors induced apoptosis and inhibited the growth of cancer cells and tumors in various cancers." (PMID 25849560, 2015). "Clinically, this study suggests AURKA as an ideal target for inhibiting cancer progression in NSCLC patients." (PMID 26036635, 2015). "Collectively, these signaling mechanisms mediated by AURKA can promote cancer cell survival and provide a chemoresistance phenotype." (PMID 25987188, 2015). "AURKA is overexpressed in various malignant tumors and its upregulation induces chromosomal instability, which leads to aneuploidy and cell transformation." (PMID 25625960, 2015). "These latter activities were of particular interest, as they not only potentially informed some roles of AURKA relevant to cancer but also connected AURKA activity to another pathological condition, autosomal-dominant polycystic kidney disease (ADPKD)." (PMID 26528438, 2015). "Together, these findings strongly suggest the key role of AURKA in tumorigenesis, and thus, underscore AURKA as an attractive target for cancer therapy." (PMID 25987188, 2015). "AURKA is frequently over expressed in different types of cancer and suppression of AURKA expression and function reduces tumor growth." (PMID 26036635, 2015).
cancer (continued). "MK-5018 also inhibits AURKB and AURKC, although at higher doses (200 folds higher than AURKA) with various IC50 values among different cancer cell lines." (PMID 25987188, 2015). "Several reports have shown that upregulation of AURKA results in resistance to anticancer agents including paclitaxel, and docetaxel in various cancers." (PMID 25625960, 2015). "We, and others, have reported that AURKA promotes survival of cancer cells through increased phosphorylation of AKT at Ser473." (PMID 25593196, 2015). "Several AURKA inhibitors have been developed to overcome AURKA-mediated pro-survival and anti-apoptotic activities in cancer cells." (PMID 25987188, 2015). "The human Aurora kinase family includes three subtypes: A, B, and C. Aurora kinase A (AURKA) and B are overexpressed in many human cancer cell-derived cell lines and cancer tissues, and are connected to carcinogenesis." (PMID 25625960, 2015). "In contrast, expression of AURKA protein is frequently observed in the cytoplasm, in addition to the nucleus, in cancer cells, suggesting an extended role of AURKA beyond regulation of mitosis." (PMID 25987188, 2015). "Various types of cancers exhibit amplification of AURKA and serious effects such as chromosomal instability, centrosomal amplification/aneuploidy, therapeutic resistance, cell-cycle progression and anti-apoptosis are induced by overexpression of AURKA." (PMID 26036635, 2015). "Inhibitors designed to block AURKA mitotic activity are currently undergoing clinical assessment as cancer therapeutics, with MLN8237/alisertib in multiple late-stage trials." (PMID 26528438, 2015). "AURKA has been found to be over-expressed in cancer cells and the AURKA gene locus is amplified in selected adult tumors." (PMID 26380223, 2015). "AURKA overexpression occurs in chromosomal region 20q13, at which gene amplification is seen in many human cancers; and is involved in colorectal, bladder, pancreatic, gastric and breast cancers." (PMID 25625960, 2015). "The ZNF217 gene belongs to the 20q13 region, a region frequently amplified in human cancers and importantly, ZNF217 protein interferes and cooperates with proteins encoded by other genes present in this region (AURKA, BCL2L1, eEF1A2)." (PMID 26431164, 2015). "Cell cycle kinases (e.g. CDC2, CDC5, CDC7 and CDC20) as well as AURKA and S100A9, which can all broadly be linked to cell cycle regulation and mitosis, were upregulated in the malignant tumors." (PMID 25226589, 2014). "The malignant tumors displayed a significantly higher module score than the benign and borderline tumors for the AURKA/proliferation, STAT1/immune response, CASP3/apoptosis, VEGF/angiogenesis and ERBb2/HER2 signaling modules." (PMID 25226589, 2014). "MLN8237 is an AURKA inhibitor whose anti-tumor activity has been confirmed in a variety of cancers; furthermore, it has been tested in phase I clinical trials." (PMID 24901229, 2014). "Numerous genes located on 20q have been reported to have altered expression as a consequence 20q gain, including several well-known cancer-related genes, such as AURKA (20q13.2), BCL2L1 (20q11.21) and AIB1 (20q12)." (PMID 23577133, 2013). "AURKA is an oncogenic kinase that enables mitotic spindle assembly, and aurora kinase A inhibitors (AKI) often induce a G2/M cell cycle arrest followed by apoptosis in cancer cell lines grown in vitro and in vivo." (PMID 23328114, 2013). "Aurora kinase A (AURKA) is an emerging target in cancer and an aurora kinase inhibitor (AKI), termed MLN8237, shows promise against MPNST cell lines in vitro and in vivo." (PMID 23328114, 2013).
cancer (continued). "Aurora Kinase A gene was highly expressed in various malignant tumors, such as oophoroma, colorectal cancer and acute myeloid leukemia." (PMID 22809428, 2012). "In particular, AURKA has been shown to have oncogenic properties and is amplified and/or overexpressed in a range of human cancers." (PMID 23226679, 2012). "In CRC, overexpression of AURKA is associated with CIN, while AURKB correlates with advanced stages and a worse patient outcome in many cancer types." (PMID 23110075, 2012). "TPX2 is an activator of AURKA (aurora kinase A), which is overexpressed in cancer and regarded as a key regulator of mitosis." (PMID 23029477, 2012). "The strong prognostic impact of AURKA in ER+/HER2- carcinomas is in agreement with the recent observation made by Haibe-Kains and co-workers." (PMID 23186136, 2012). "As undifferentiated tumors are more aggressive and metastatic, we can suggest that UBE2C and AURKA are overexpressed in malignant tumors." (PMID 20630075, 2010). "Of these chromosome 20 genes, only ZNF217 (FDR 2.67e-2, cancer/normal ratio 1.57) and AURKA (FDR 5.52e-5, cancer/normal ratio 2.32) were also significant in the LCM data set." (PMID 19419571, 2009). "This suggests that AURKA and TPX2 are strong candidates for the target of chromosome 20q amplification, and play critical causal roles in cancer development." (PMID 19259408, 2008). "AURKA is a validated therapeutic target for treatment of cancers and there currently are small molecule inhibitors of aurora kinases being evaluated in the clinic." (PMID 18714348, 2008). "Overexpression of AURKA enables cells to bypass the G2 DNA-damage checkpoint, resulting in centrosome amplification and genomic instability features commonly observed across multiple cancer types." (PMID 41515655, 2026). "Owing to its role in cancer, AURKA is considered a potential pharmacological target." (PMID 39928563, 2025). "Both AURKA and PLK1 are serine/threonine-protein kinases, have been implicated in gliomagenesis, and are potential drug targets (with ongoing clinical trials) for many different cancers." (PMID 39565278, 2025). "Next, we investigated the genomic characteristics of AURKA in pan-cancer." (PMID 40718709, 2025). "This analysis led to discovery that AURKA inhibitors may be effective in cancers where tumour suppressors like FBXW7 or NSD1 are compromised." (PMID 40775769, 2025). "Similarly, dysregulation of AURKA plays a crucial role in the tumorigenesis and development of various cancers, including PCa." (PMID 40626556, 2025). "Dysregulated Aurora kinase A (AURKA) has been shown to mediate various cancer types." (PMID 40872590, 2025). "In addition to its role in mitotic control, AURKA influences the tumor microenvironment by affecting pathways essential for EMT—a critical process for cancer invasion and metastasis." (PMID 40723362, 2025). "Gene amplification and overexpression of AURKA have been observed in various cancers, and a relationship between AURKA overexpression and poor prognosis has also been reported, suggesting that AURKA may function as an oncogenic driver." (PMID 40546348, 2025). "AURKA serves also as a therapeutic cancer target that is often overexpressed in several cancers." (PMID 40057470, 2025). "Dysregulation or overexpression of AURKA leads to centrosome amplification and faulty spindle formation, which, in turn, result in chromosomal mis-segregation during mitosis, contributing to aneuploidy—a key characteristic of cancer development." (PMID 40723362, 2025). "Constitutively active RAS is also seen to promote AURKA expression in cancer cells." (PMID 40568758, 2025).